ENSG00000252550
Gene: Small nucleolar RNA gene on chromosome 13 (105,897,523 to 105,897,643, reverse strand). Ensembl gene ENSG00000252550.
Homologues: Paralogues in human: SNORA25B (78% identical), SNORA25 (76% identical).